HOXA1 (homeobox A1)
Diseases named in the same sentence as HOXA1 in open-access papers (continued):
Sharing a sentence is not in itself a finding about the gene and the disease.
gastric cancer (13 papers, 2013 to 2025). A primary or metastatic malignant neoplasm involving the stomach. "Kaplan‐Meier survival analysis revealed that elevated HOXA1 levels were associated with worse overall (P = 5.3 × 10−3) and event‐free (P = 8.0 × 10−3) survival of gastric cancer patients." (PMID 40995693, 2025). "In gastric cancer cell lines, HOXA1 increases cell cycle progression by increasing cyclin D expression." (PMID 40076953, 2025). "‐Blocking HOXA1‐PITX2 interaction by nortriptyline suppresses progression of gastric cancer, highlighting HOXA1/PITX2 axis as a novel therapeutic target for lysosomal exocytosis‐mediated SASP in cancers." (PMID 40995693, 2025). "To explore their capacity for liquid–liquid phase separation (LLPS), we observed the formation of nuclear puncta in AGS gastric cancer cells expressing EGFP‐tagged PITX2 or endogenous HOXA1, which were augmented under SD condition." (PMID 40995693, 2025). "In gastric cancer, miR-10a-5p represses cell growth, migration and invasion through silencing HoxA1." (PMID 29615098, 2018). "Preclinical studies demonstrate that Nor administration attenuates lysosomal exocytosis‐mediated senescence‐associated secretory phenotype (SASP) and reduces aggressive phenotypes in gastric cancer models, underscoring the HOXA1/PITX2 axis as a critical regulator of gastric cancer progression." (PMID 40995693, 2025). "Regarding the differential effect of PCDHGA9 on the Wnt/β-catenin pathway between CRC and gastric cancers, varying HOXA1 and CXCR4 expression levels in these cancers might explain this difference." (PMID 39587482, 2024). "Most have previously been proposed as biomarkers in a specific tumor (or tumor-related condition): C15orf48 in esophageal cancer, NF2 in neurofibromatosis, CMTM6 in renal adenocarcinoma, PLEK2 in lung adenocarcinoma, RRM2 in glioma, HOXA1 in breast and gastric cancers, and SAA2 in renal cancer." (PMID 34204789, 2021). "In addition, elevated HOXA1 expression enhances cell proliferation, invasion, and metastasis in prostate cancer, and higher levels of HOXA1 correlates with accelerated cell proliferation and poor prognosis in gastric cancer." (PMID 30376874, 2018). "Compared to their para‐tumoral tissues, higher levels of HOXA1, PITX2, MCOLN1, and RAB3A were observed in gastric cancer specimens." (PMID 40995693, 2025). "We further conducted rescue experiments to explore the functional interplay between HOXA1 and PITX2 in lysosomal exocytosis and aggressiveness of gastric cancer." (PMID 40995693, 2025). "Clinically, elevated expression of HOXA1, PITX2, MCOLN1, RAB3A, LGALS1, and IGFBP7 constitutes a prognostic signature correlating with poor outcomes of gastric cancer patients." (PMID 40995693, 2025). "HOXA1 presents up‐regulated pattern in gastric cancer (GC) tissues." (PMID 33942991, 2021). "This study focused on the expression and clinical significance of HOXA1 in gastric cancer (GC)." (PMID 26791264, 2016). "In this study, we found that 1‐83 amino acids of HOXA1 was able to interact with N‐terminal transactivation domain of PITX2, resulting in enhanced PITX2 activity to drive transcription of MCOLN1 and RAB3A in gastric cancer cells." (PMID 40995693, 2025). "Our data demonstrated that HOXA1 facilitated the progression of gastric cancer, at least in part, via its interaction with PITX2, indicating the pivotal functions of HOXA1/PITX2 axis in the progression of gastric cancer." (PMID 40995693, 2025).
glioblastoma (13 papers, 2016 to 2023). The most malignant astrocytic tumor (WHO grade IV). "Over-expression of HOTAIRM1 up-regulates HOXA1, which then increases the invasiveness of glioblastoma." (PMID 35521558, 2022). "For instance, over-expressed lncRNA HOXA transcript antisense RNA, myeloid-specific 1 (HOTAIRM1), facilitates tumor growth and invasion through up-regulating HOXA1 and sequestering G9a/EZH2/Dnmts away from the HOXA1 gene in glioblastoma multiforme." (PMID 31680832, 2019). "HOXA1 has also been reported to participate in temozolomide resistance in glioblastoma cell lines through the regulation of the homologous recombinant DNA repair pathway." (PMID 27399693, 2016). "In glioblastoma multiforme (GBM), the HOTAIRM1 lncRNA oncogene, which is transcribed from the antisense direction of the HomeoboxA1 (HOXA1) gene, binds and sequesters G9a away from the HOXA1 gene promoter." (PMID 35740522, 2022). "It was a tumor suppressor in glioblastoma multiform, and downregulation of HOTAIRM1 usually inhibited tumor growth and invasion by regulating HOXA1 expression." (PMID 35350655, 2022). "Thus, in addition to the epigenetic modulation of HOXA1 and the sponging hsa-miR-129-5p and hsa-miR-495-3p, sponging of hsa-miR-17-5p (and potentially other TGM2-binding miRNAs) by HOTAIRM1 may cause increased TGM2 mRNA and protein expression in glioblastoma." (PMID 34584066, 2021). "For instance, lncRNA HOTAIRM1 facilitates glioblastoma multiforme (GBM) progression by mediating H3K9 and H3K27 histone demethylation and reduces DNA methylation levels by sequestering DNA methyltransferases away from the TSS of the HOXA1 gene." (PMID 37993428, 2023). "LncRNA HOTAIRM1 (HOX antisense intergenic RNA myeloid 1), which is located between the HOXA1 and HOXA2 genes, could interact with DNMTs and other epigenetic factors to sequester them away from HOXA1 promoter in glioblastoma multiforme (GBM)." (PMID 36533073, 2022). "Expression analysis based on TCGA data indicated that HOXA1 was significantly upregulated in most cancer types, including CESC (cervical squamous cell carcinoma and endocervical adenocarcinoma), LGG (low-grade glioma), GBM (Glioblastoma multiforme), and HNSCC." (PMID 36119466, 2022).
melanoma (13 papers, 2014 to 2025). A malignant, usually aggressive tumor composed of atypical, neoplastic melanocytes. "Eighty-four TGF-β signaling genes were associated with HOXA1 expression, indicating that HOXA1 drives melanoma progression through interaction with the TGF-β signaling axis." (PMID 39858044, 2025). "In addition, HOXA1 promotes melanoma tumor growth and metastasis, and is associated with poor clinical outcome." (PMID 26417931, 2015). "Lastly, bioinformatics analysis uncovered that patients with high HOXA1 had a highly invasive melanoma signature and a reduced time to distant metastasis formation." (PMID 39858044, 2025). "Transcriptome analysis of HOXA1 endogenous melanoma cells revealed upregulation of TGF-β signaling and downregulation of melanocyte-inducing transcription factor (MITF)." (PMID 39858044, 2025). "HOXA1 demonstrated pro-invasion capabilities in human melanoma cell lines as well, where immortalized melanocytes that overexpressed HOXA1 had enhanced invasion and invasive morphological changes." (PMID 39858044, 2025). "For example, HOXA1 drives melanoma growth and metastasis via diverse cytokine pathways, including the TGFβ signaling axis." (PMID 37439014, 2023). "The transcriptome profiling and pathway analysis of HOXA1 expressing melanoma cells showed increased TGF-β signaling." (PMID 34617205, 2022). "HOXA1, a lncRNA overexpressed in cancers such as breast, melanoma, and oral carcinomas, drives metastasis and tamoxifen resistance." (PMID 33819300, 2021). "HOXA1 dedifferentiates melanoma cells into a highly aggressive cell state accompanied by TGF activation." (PMID 33763449, 2020). "Studies have found that in hypoxic areas of SCLC and melanoma, miR-210 regulates the expression of HOXA1 and inhibits the anti-tumor effect of cytotoxic T lymphocyte." (PMID 33763449, 2020). "Through the TGFβ signaling axis and other cytokine pathways, HOXA1 may regulate TUBB4A to drive melanoma growth and metastasis, which should be proven by experimental studies in the future." (PMID 37439014, 2023). "The expression of HOXA1 could stratify melanoma patients based on metastatic potential and hence function as a potential prognostic marker." (PMID 34617205, 2022). "For example, the high expression level of HOXA1 promotes distant metastasis of melanoma." (PMID 30376874, 2018). "Furthermore, the involvement of particular HOX genes such as HOXC13, HOXD3, HOXA1 in metastasis and invasiveness was recently demonstrated for melanoma, breast and prostate cancer, respectively." (PMID 27363011, 2016). "Indeed, HOXA1 has been identified as a driver of both oncogenesis and the invasion-metastasis cascade in human melanoma." (PMID 24586203, 2014). "Therefore, the downregulation of MITF in melanoma cells with enhanced HOXA1 expression may lead to melanocyte de-differentiation and thus an invasive phenotype due to the upregulation of TGF-β activation." (PMID 39858044, 2025). "Therefore, HOXA1 is a prognostic biomarker for highly invasive melanoma and metastasis." (PMID 39858044, 2025).
pancreatic cancer (12 papers, 2015 to 2025). "In pancreatic cancer, for example, it has been described that the downregulation of HOXA1, HOXB1 and HOXB3 by miR-10a is associated with the formation of metastasis." (PMID 33375038, 2020). "In PDAC, aberrant expression of several HOX transcription factors has been described and functional studies have shown that HOXA10, HOXB7, and HOXC11 promote pancreatic cancer development while HOXA1, HOXB1, and HOXB3 act as tumor-suppressors." (PMID 40619489, 2025). "In micro-dissected pancreatic tumors, HoxA1 protein is overexpressed in pancreatic cancer and negatively correlates with miR-10a." (PMID 31137902, 2019). "The overexpression of miRNA-10a has been observed to down-regulate the transcriptional suppressors and metastatic factors (homeobox transcription factors)—HOX (HOXB1, HOXB2, HOXA1) in various pancreatic cancer cell lines including, PANC-1, CAPAN-1, SUIT-2, KP-2 and MIA PaCa-2." (PMID 39200178, 2024). "However, inhibition of HoxA1 promotes the invasiveness of pancreatic cancer cells." (PMID 31137902, 2019). "SPSB4 was identified among five genes, ADAMTS2, HOXA1, PCDH10, SEMA5A and SPSB4, that were highly/frequently methylated in liquid biopsies of pancreatic cancers although with a relatively low potential compared with the other four markers." (PMID 34062897, 2021). "Of the three criteria, we identified eight genes that were the most highly/frequently methylated in pancreatic cancers (PCDH10, SPSB4, HOXA1, ADAMTS2, BMP3, C13orf18, CCND2, and SEMA5A)." (PMID 32520974, 2020). "MiR-10a is upregulated in various tumors, including pancreatic cancer, especially in malignant and metastatic tumors, and exhibits functions, such as tumor migration and invasion through PTEN and HOXA1." (PMID 33809988, 2021). "In pancreatic cancer cells, HOTTIP regulates HOXA10, HOXB2, HOXA11, HOXA9 and HOXA1, but not HOXA13." (PMID 30819158, 2019). "However, another study in pancreatic cancer cells demonstrated that HOTTIP did not modulate HOXA13 expression, but did regulate the expression of other HOX genes such as HOXA1, HOXA9, HOXA10, HOXA11 and HOXB2." (PMID 28938659, 2017).
small cell lung carcinoma (12 papers, 2015 to 2024). Small cell lung cancer (SCLC) is a highly aggressive malignant neoplasm, accounting for 10-15% of lung cancer cases, characterized byrapid growth, and early metastasis. "Downregulation of HOXA1 was associated with chemoresistance to cisplatin, adriamycin, and etoposide in small cell lung cancer." (PMID 31568655, 2020). "Ranked No. 5 is HOTAIR, and the literature found that HOTAIR affects the drug resistance of small cell lung cancer cells by regulating the methylation of HOXA1." (PMID 33794766, 2021). "For instance, HOXD10 and miR-146a are associated with head and neck squamous cell carcinomas, and HOXA1, under the regulation of miR-100, in small-cell lung cancer." (PMID 26565624, 2015). "Furthermore, evidence suggests that HOXA1, functioning as a tumor suppressor gene, participates in the regulation of chemoresistance in small cell lung cancer (SCLC) through the NF-KB signaling pathway." (PMID 38311789, 2024). "Also, the expression of microRNA‐100 affects small cell lung cancer cell survival and chemoresistance by downregulating HOXA1 gene." (PMID 33660436, 2021). "In small cell lung cancer (SCLC), HOTAIR was found to inhibit expression of DNMT1 and DNMT3B, thus regulating the methylation of HOXA1 to mediate chemoresistance of SCLC." (PMID 36533073, 2022). "HOXA1 is dysregulated in various cancers, for example it is overexpressed in OSCC (where it promotes cell proliferation) and is downregulated in small cell lung cancer." (PMID 26179909, 2015). "The hypermethylation of HOXA1 may be regulated by H3K27me3 through HOTAIR, thereby contributing to the development of chemoresistance in small-cell lung cancer (SCLC)." (PMID 38311789, 2024). "In small-cell lung cancer, HOTAIR could induce HOXA1 methylation and lead to multidrug resistance through the NF-κB pathway." (PMID 36471329, 2022). "HOXA1 and HOXA7 were expressed in small cell lung cancer, while they were not expressed in normal lungs." (PMID 34606634, 2021).
glioma (10 papers, 2011 to 2023). A benign or malignant brain and spinal cord tumor that arises from glial cells (astrocytes, oligodendrocytes, ependymal cells). "They found that HOXA2 was significantly increased and associated with lncRNA HOTAIRM1 like HOXA1 in glioma." (PMID 37351805, 2023). "Many HOMEOBOX (HOX)-related genes (HOXD11, HOXD9, HOXC10, HOXC11, HOXC6, HOXB3, HOXA2, HOXA1) were associated with a glioma grade and significantly overexpressed in GIV (Wilcoxon rank-sum and BH padj < 0.05)." (PMID 36850002, 2023). "Our results showed that HOXA1 expression levels were significantly up-regulated in glioma tissues compared with that in normal brain tissues, and HOXA1 expression levels were associated with the grade malignancy of glioma." (PMID 30376874, 2018). "To investigate the expression levels of HOXA1 in GBM, we examined the HOXA1 mRNA levels in tumor tissues from 40 patients with glioma (WHO I and II, n = 20; WHO III and IV, n = 20) and 20 normal brain tissues using qPCR." (PMID 30376874, 2018). "Moreover, several of them (e.g., HOXA1, A5, A6, A7, A10, D9, and D10) were expressed in most IDHwt glioma samples, constituting thus the core HOX signature in IDHwt samples, whereas HOXB1, HOXC12, HOTTIP, and HOXB‐AS4 were not reactivated." (PMID 33720519, 2021). "Accordingly, all members, but HOXD10, of the core HOX signature of IDHwt samples (i.e., upregulation of HOXA1, A5, A6, A7, A10, D9, and D10) have an oncogenic role in gliomas, by promoting cell viability and migration or by reducing cell death of GBM cell lines." (PMID 33720519, 2021). "By analyzing data from The Cancer Genome Atlas (TCGA), we found that HOXA1 was aberrantly upregulated in multiple cancers, and that elevated HOXA1 was significantly associated with poor prognosis of post-radiotherapy head and neck squamous cell carcinoma (HNSCC) and low-grade glioma (LGG) patients." (PMID 36119466, 2022).
oral squamous cell carcinoma (9 papers, 2012 to 2024). "Immunohistochemical analysis using a tissue microarray (TMA) containing 127 oral squamous cell carcinomas (OSCC) was performed to determine the prognostic role of HOXA1 expression." (PMID 22498108, 2012). "The expression level of HOXA1 is correlated with poor prognosis of oral squamous cell carcinoma." (PMID 26080812, 2015). "A new investigation established that HOXA1 which is a homeobox (HOX) gene, is highly expressed in oral squamous cell carcinomas." (PMID 32281284, 2020). "In oral squamous cell carcinoma (OSCC), AFAP1-AS1 expression is enhanced and its inhibition can suppress the proliferation, migration, and invasion, while promoting cell apoptosis via affecting the miR-145/HOXA1 axis." (PMID 34335760, 2021).
prostate carcinoma (9 papers, 2016 to 2024). A carcinoma that arises from epithelial cells of the prostate gland. "In addition, HOXA1 was found to enhance cell invasion, proliferation, and metastasis of prostate cancer cells." (PMID 31507632, 2019). "For example, ACPP (PIP = 0.999) was overexpressed in prostate cancer cell lines and HOTAIRM1 (PIP = 0.999) is antisense of HOXA1 and found to be highly expressed in prostate cancer cells enhancing cell proliferation, invasion, and metastasis." (PMID 38887957, 2024). "HOXA13, HOXA1, HOXA5, HOXA6, HOXA7, HOXA9, and HOXA10 are involved in prostate cancer, and they form a DNA loop with a locus that induces prostate cancer and regulates gene transcription." (PMID 37590265, 2023). "Down-regulation of HOXA1 can increase the expression of E-cadherin while reducing the expression of Snail and MMP-3, which can inhibit ERK1/2 and AKT to suppress the growth, migration, invasion and metastasis of prostate cancer." (PMID 33763449, 2020).
non-small cell lung carcinoma (8 papers, 2018 to 2025). A group of at least three distinct histological types of lung cancer, including non-small cell squamous cell carcinoma, adenocarcinoma, and large cell carcinoma. "The putative target for miR-10a, HOXA1 mRNA (homeobox protein A1) was upregulated 3-9-fold in 16HBE-T cells compared to controls; HOXA1 is a protein that is highly expressed in non-small-cell lung cancer (NSCLC) and is associated with lower survival in patients." (PMID 38069307, 2023). "For example, in non-small cell lung cancer, HOXA1 promotes cell proliferation by activating the TGF-β/SMAD3 pathway." (PMID 40076953, 2025). "The association of HOXA-AS2, HOXA11,HOTTIP, HOXA1, HOXA3 and HOXA4 expression with survival of non-small-cell lung cancer." (PMID 39121297, 2024). "miR-100-5p inhibits cell proliferation, migration, and invasion, as well as signaling pathways such as Wnt/β-catenin, particularly in non-small cell lung cancer (NSCLC), where it targets HOXA1 to suppress tumor progression and epithelial-mesenchymal transition (EMT)." (PMID 41329722, 2025).
acute myeloid leukemia (6 papers, 2012 to 2024). Acute myeloid leukemia (AML) is a group of neoplasms arising from precursor cells committed to the myeloid cell-line differentiation. "Humans possess 39 HOX genes across seven families, with specific genes like HOXB3, HOXB4, and HOXA1 to HOXA10 linked to adverse outcomes in diseases such as acute myeloid leukemia (AML)." (PMID 39200378, 2024). "In hematopoietic cells, overexpression of HOXA1 blocked differentiation, leading to transformation by colony formation in soft agar assays and to the development of acute myeloblastic leukemia in lethally irradiated mice." (PMID 22498108, 2012).
Bosley-Salih-Alorainy syndrome (6 papers, 2007 to 2017). "Diseases associated with HOXA1 mutations include Athabaskan Brainstem Dysgenesis Syndrome and Bosley-Salih-Alorainy syndrome." (PMID 28968992, 2017). "These HOXA1 mutations result in two overlapping, but distinct syndromes which have been described as the Bosley-Salih-Alorainy syndrome and the Athabaskan brainstem dysgenesis syndrome." (PMID 28380068, 2017). "A recent study in humans revealed that mutations in Hoxa1 can cause severe cardiovascular malformations in patients with Bosley-Salih-Alorainy Syndrome." (PMID 24086288, 2013). "Homozygous mutations of HOXA1 are associated with the autosomal recessive Athabascan Brainstem Dysgenesis Syndrome (ABDS) and the Bosley-Salih-Alorainy Syndrome (BSAS) characterized by sensorineural deafness due to the absence or aplasia of the cochlea." (PMID 28469562, 2017).